TLR4 (toll like receptor 4)
Diseases named in the same sentence as TLR4 in open-access papers (continued):
Sharing a sentence is not in itself a finding about the gene and the disease.
Obstructive Sleep Apnea (4 papers, 2013 to 2023). "No studies to our knowledge have evaluated the levels of TLR4 in the CNS, although recently, upregulated TLR4 levels have been reported on circulating monocytes in adults with obstructive sleep apnea." (PMID 24324707, 2013). "miR-21-5p Under-Expression in Patients with Obstructive Sleep Apnea Modulates Intermittent Hypoxia with Re-Oxygenation-Induced-Cell Apoptosis and Cytotoxicity by Targeting Pro-Inflammatory TNF-α-TLR4 Signaling." (PMID 36671757, 2022).
onchocerciasis (4 papers, 2017 to 2024). Onchocerciasis is a form of filariasis, caused by the parasitic worm Onchocerca volvulus, transmitted by the black fly. "Studies on TLR4-deficient mice and those with natural TLR4 mutations (C3H/HeJ) have revealed increased susceptibility to various infections including onchocerciasis, due to impaired sensing by the innate immune system." (PMID 39432476, 2024). "The importance of TLRs in mediating interactions between helminthic parasites and the human host immune system has also been described and the TLR4 pathway has been implicated in host immunity to onchocerciasis." (PMID 33494344, 2021). "The built-in adjuvant was specifically selected to interact with TLR4 based on the role of this receptor in onchocerciasis immunity." (PMID 33494344, 2021). "The filarial endosymbiont Wolbachia is known to elicit immune responses through TLR2 and TLR4 and is known to be the major mediator of inflammatory responses in lymphatic filariasis and onchocerciasis." (PMID 29225962, 2017). "TLR2 is a receptor that plays an important role in filarial infection; the filarial endosymbiont Wolbachia is known to elicit immune responses through TLR2 and TLR4 and is known to be the major mediator of inflammatory responses in lymphatic filariasis and onchocerciasis." (PMID 29225962, 2017).
Oral ulcer (4 papers, 2022 to 2026). Erosion of the mucous mebrane of the mouth with local excavation of the surface, resulting from the sloughing of inflammatory necrotic tissue. "Among them, gingival overgrowth, oral ulcer, and bruxism were all associated with both biomarkers, suggesting possible synergistic effects between TLR4 and FLT3." (PMID 40362543, 2025).
Peritoneal Fibrosis (4 papers, 2013 to 2024). Disorder characterized by a wide range of structural changes in PERITONEUM, resulting from fibrogenic or inflammatory processes. "Together, these findings indicated a major role for TLR2 and to a lesser extent for TLR4 in bacteria-induced peritoneal fibrosis associated with PD, and pointed at controlling infection-induced TLR-mediated activation as a potential therapeutic against peritoneal fibrosis." (PMID 30538643, 2018). "The activation of TLR4 by LPS in peritoneal mesothelial cells might result in a massive influx of leukocytes in the peritoneal cavity, leading to the development of peritoneal dysfunction or peritoneal fibrosis." (PMID 24219662, 2013). "Additionally, the use of antibody blockade targeting TLR2, TLR4, or C5aR showed considerable inhibitory effects on the bacteria-induced release of pro-fibrotic and pro-inflammatory mediators by peritoneal leukocytes in cases of infection-related peritoneal fibrosis." (PMID 39749340, 2024).
polyarthritis (4 papers, 2013 to 2025). "QLY and XYQLY eased polyarthritis in AIA rats after repeated doses, which reflected in reduced inflammation and bone degradation and downregulated p-p65, MMP3, and TLR4 expressions in joints." (PMID 35509625, 2022).
renal dysfunction (4 papers, 2014 to 2024). "These molecules contribute to the increased expression of TLR4 and caspase 3 in renal tubular cells, leading to the development of acute renal dysfunction through cell damage and apoptosis of these cells." (PMID 38139297, 2023). "Moreover, it should be noted that in some patients without renal dysfunction increased levels of urinary TLR4 were also observed, suggesting that urinary excretion of TLR4 may be associated with systemic inflammation." (PMID 38139297, 2023). "Moreover, a strong correlation was evident between the expressions of TLR-4, TLR-2, NF-κB, and TNF-α genes and hepato-renal dysfunction indicators." (PMID 37045926, 2023).
retinal (4 papers, 2014 to 2025). "LPS elicits retinal inflammation through activation of TLR-4, which is expressed in RPE cells, leading to inflammatory cytokine release and causing several degenerative processes." (PMID 35069225, 2021). "However, the role of two Tlr4-dependent signaling cascades, myeloid differentiation primary response 88 (Myd88) and TIR-domain-containing adapter inducing interferon-β (Trif), in retinal IR injury is poorly understood." (PMID 24754835, 2014).
sporotrichosis (4 papers, 2017 to 2026). The commonest and least serious of the deep mycoses, characterized by nodular lesions of the cutaneous and subcutaneous tissues. "At present, more than ten TLRs are known, but only TLR-2 and TLR-4 have been involved in the immune response induced by sporotrichosis during the recognition of S. schenckii by macrophages and its inflammatory activation." (PMID 34358055, 2021). "TLR-2 and TLR-4 have been reported to be involved in the sporotrichosis-induced immune response." (PMID 38172590, 2024). "Contrary to the previously published data, we found a lesser important role for TLR4 during human PBMCs interaction than that reported in the model of murine sporotrichosis; most probably due to the natural differences between the animal and human immune cells." (PMID 28539922, 2017). "In TLR-4-deficient mice, the TGF-β secretion increases, which could indicate that the secretion of this cytokine could negatively affect the inflammatory activation of macrophages during sporotrichosis in mice." (PMID 34358055, 2021). "In peritoneal macrophages of mice with sporotrichosis, a correlation has been shown between the presence of TLR-4 and the secretion of both pro-inflammatory (TNF-α) and anti-inflammatory (IL-10) mediators during sporotrichosis." (PMID 34358055, 2021).
Stillbirth (4 papers, 2018 to 2022). Death of the fetus in utero after at least 22 weeks of gestation. "As we expected, the serum levels of TLR4, IL-6 and IL-1β had higher concentration in the stillbirth sow group." (PMID 36741405, 2022). "Surprisingly, the stillbirth rate was abnormal in only 5% of Tlr4−/− mothers that carried Tlr4+/− fetuses." (PMID 29440369, 2018). "In fact, the very low stillbirth incidence for the heterogenic Tlr4−/−/Tlr4+/− maternal-fetal combination implies that TLR4 acts in the fetal compartment to confer robust protection against increased stillbirth incidence in MiP." (PMID 29440369, 2018). "Nevertheless, infection in Tlr4−/− pregnant females was less deleterious to the fetuses, partially restoring the stillbirth incidence." (PMID 29440369, 2018). "The concentration of TLR4 in the serum was also higher in the stillbirth sow group although this did not achieve the statistical significance level." (PMID 36741405, 2022). "Nevertheless, this result is not fully attributable to the absence of maternal TLR4, as Tlr4−/− isogenic pregnancies showed an abnormal stillbirth incidence of 35%." (PMID 29440369, 2018).
thyroid (4 papers, 2024 to 2025). "Currently, research has shown that the TLR4/NF-κB signaling axis may exert a significant influence on the development of thyroid disorders caused by various factors." (PMID 39771102, 2024). "However, it remains unclear whether VD intervention can ameliorate arsenic-induced thyroid damage and if its antagonistic mechanism is associated with the TLR4/NF-κB signaling pathway." (PMID 39771102, 2024). "Later, it has been proven that TLR4 activation by LPS is able to trigger thyroiditis in NOD H2h4 mice." (PMID 37824030, 2024). "Population studies have consistently observed that the TLR4/NF-κB signaling pathway is frequently activated in patients with various thyroid diseases, and is closely related to thyroid dysfunction and the abnormal expression of THs synthesis-related genes." (PMID 39771102, 2024). "The results confirm that the efficacy of the TAK-242 intervention can reduce arsenic-induced thyroid inflammatory injury and dysfunction by inhibiting the TLR4/NF-κB signaling pathway, thereby reducing the arsenic-induced inflammatory damage and dysfunction of the thyroid gland." (PMID 39771102, 2024). "The LPS receptor, Toll-like receptor 4, is expressed in thyroid follicular cells, and LPS increases TPO (a major thyroid autoantigen) expression via the NF-κB pathway." (PMID 41170176, 2025).
Urothelial Bladder Carcinoma (4 papers, 2021 to 2024). "tiRNA-Gly-GCC-1 was discovered to diminish TLR4 expression via directly targeting 3ʹUTR of TLR4 in urothelial bladder carcinoma." (PMID 38289488, 2024).
Ventricular arrhythmia (4 papers, 2022 to 2025). "Increased METTL3 elevates m6A modification of TLR4 and up-regulates its expression, which promotes sympathetic hyperactivity via the TLR4/NF-κB pathway and increases the incidence of ventricular arrhythmias post-MI." (PMID 37671161, 2023). "Activation of the TLR4/CaMKII signaling pathway is related to vulnerability to ventricular arrhythmias in myeloid differentiation protein 1 (MD1) deletion mice after MI227." (PMID 35273164, 2022).
abortion (3 papers, 2018 to 2025). the ending of pregnancy by removing a fetus or embryo before it can survive outside the uterus. "For instance, demonstrated that levels of IL5, IL6, IL1-ß, TNF-α, TLR4, and Tollip were significantly up-regulated in ewes affected with abortion than in resistant ones, while SOD and CAT gene patterns elicited an opposite trend." (PMID 40872670, 2025). "In Barki sheep, found that differences in the nucleotide sequences of the TLR4 and SOD genes were linked to an increased risk of abortion." (PMID 40872670, 2025). "We have included three important and different in function Toll-like receptors (TLR2, TLR4, and TLR9) to study the relation between TLR SNPs and risk of spontaneous abortion." (PMID 30116270, 2018). "Next factors that can also be considered when predicting the risk of spontaneous abortion are SNPs in TLR2, TLR4, IL-6, IL-8, and PGR genes." (PMID 30116270, 2018).
abscesses (3 papers, 2010 to 2024). "Experiments with barcoded E. coli revealed that TLR4 mediates a tradeoff between abscess formation and bacterial clearance." (PMID 38096412, 2023). "Within this framework, diminishing inflammatory responses is expected to reduce development of abscesses; indeed, mice lacking TLR4, the membrane-bound receptor for lipopolysaccharide, do not develop abscesses." (PMID 38227662, 2024). "We characterized the early hepatic response with single-cell RNA sequencing and found that mice with reduced activation of early inflammatory responses, such as those lacking the LPS receptor TLR4 (Toll-like receptor 4), are resistant to abscess formation." (PMID 38096412, 2023). "These defects are phenocopied in mice lacking the LPS receptor TLR4 (Toll-like receptor 4), which are comparably resistant to abscess formation." (PMID 38096412, 2023). "B6J females lacking TLR4 had elevated hepatic bacterial burdens compared to WT B6J or TLR4Het littermates that did not form abscesses." (PMID 38096412, 2023). "Since commensal E. coli can elicit abscess formation and TLR4KO animals do not develop abscesses, we propose that abscesses result from exuberant TLR4-driven immune responses, rather than specific pathogen-derived virulence factors, which drive Staphylococcus aureus–induced renal abscesses." (PMID 38096412, 2023). "Since many of the phenotypes observed at 4 hpi are likely induced by LPS stimulation via the LPS receptor Toll-like receptor 4 (TLR4), we examined whether mice lacking TLR4 (in a B6J background) were resistant to abscess formation." (PMID 38096412, 2023). "Kidneys of Tlr4−/− and Myd88−/− mice infected with CFT073 or the ΔTcpC mutant were normal in size, color and texture and had no abscesses." (PMID 20886104, 2010).
Acanthamoeba keratitis (3 papers, 2014 to 2019). Keratitis due to infection by acanthamoeba; it is usually associated with soft contact lens wear, particularly overnight wear. "Our results not only confirmed their findings but also demonstrated that pathogenic strains of Acanthamoeba are recognized by TLR4 in Chinese hamster model of Acanthamoeba keratitis." (PMID 24633052, 2014). "isolated from a patient with Acanthamoeba keratitis and from environmental water samples, TLR2 and TLR4 showed increased expression in pneumocytes, interstitial cells, and epithelial cells of the bronchial tree." (PMID 31309100, 2019). "isolated from a patient with Acanthamoeba keratitis (Ac55) and Malta Lake (Ac43), the levels of expression of TLR2 were statistically higher than the levels of expression of TLR4." (PMID 27511368, 2016).
Acute Aortic Dissection (3 papers, 2018 to 2021). "However, there is lacking research on serum TLR4 levels in acute aortic dissection (AAD) patients, and the performance of serum MMP9 and TLR4 for the diagnosis of AAD is still unknown." (PMID 30497388, 2018).
age-related macular degeneration (3 papers, 2019 to 2023). Age-related loss of vision in the central portion of the retina (macula), secondary to retinal degeneration. "Reports linked TLR4 polymorphisms to AMD susceptibility, and the role of TLR agonists (e.g. DAMPs) and the outcomes in age-related macular degeneration (AMD) have been well studied in particular the role of Carboxyethyl pyrrole (CEP)." (PMID 38045700, 2023).
airway allergy (3 papers, 2015 to 2017). "This hypothesis was corroborated by in vivo experiments, and adoptive transfer with Pplase-primed DCs facilitated the development of airway allergy induced by OVA, which was abolished by the blockade of TLR4 signals." (PMID 28240301, 2017).
alcohol addiction (3 papers, 2019 to 2021). "The contribution of this mechanism in ALD pathogenesis has been strongly demonstrated in TLR4 knockout mice experiments characterized by acquired resistance to both alcohol addiction and liver-damaging." (PMID 34630107, 2021). "More studies are needed to disentangle the exact role of TLR4 signaling in alcohol addiction-related effects." (PMID 33424612, 2020). "Indeed, the activation of innate immunity and TLR4 signaling appear to be essential for alcohol addiction-like behaviors." (PMID 33424612, 2020).
allergic conjunctivitis (3 papers, 2016 to 2020). "In this work, we observed an increased expression of TLR4 in the CD4 T+ cells of patients with perennial allergic conjunctivitis (PAC)." (PMID 33114004, 2020). "Remarkably, when we stimulated PBMC in patients with perennial allergic conjunctivitis with Der p, we observed that TLR4 and CD69 were increased in CD4+T cells, suggesting that allergen-specific stimulation also induces TLR4." (PMID 33114004, 2020). "This study aimed to evaluate the involvement of toll-like receptor 4 (TLR4) and α-melanocyte stimulating hormone (α-MSH) in the immune regulation associated with perennial allergic conjunctivitis (PAC)." (PMID 33114004, 2020). "Allergic conjunctivitis to Short Ragweed pollen required TLR4 to drive the production of TSLP/OX40L and the priming of a productive Th2 response." (PMID 31164097, 2019). "Further studies isolating CD4+TLR4+ cells from blood samples from allergic conjunctivitis patients and stimulating them with Der p are needed to determine if CD4+TLR4+ cells have a role in the induction of the IL-6 pro-inflammatory microenvironment and the inhibition of Treg cells." (PMID 33114004, 2020). "Thus, this study aimed to evaluate the potential involvement of TLR4/α-MSH in CD4-activated cells in patients with perennial allergic conjunctivitis." (PMID 33114004, 2020). "Remarkably, when we stimulated the PBMC of patients with perennial allergic conjunctivitis with Der p, we observed an increased TLR4 and CD69 in CD4+T cells, suggesting that allergen-specific stimulation also induces TLR4." (PMID 33114004, 2020). "This work aims to evaluate the potential involvement of TLR4/α-MSH in CD4+T cells and their functional impact in the cells of patients with perennial allergic conjunctivitis." (PMID 33114004, 2020). "In order to explore whether CD4+TLR4+ cells were induced by Ag-specific stimulation (Der p) or by LPS stimulation, we obtained peripheral blood mononuclear cells (PBMC) from patients with perennial allergic conjunctivitis." (PMID 33114004, 2020). "In sum, the activation of CD4+TLR4+T cells by the antigen and TLR induces an inflammatory microenvironment characterized by TNF-α, IL-6, and IL-4, which favors a lack of immune regulation in perennial allergic conjunctivitis." (PMID 33114004, 2020).
anxiety disorder (3 papers, 2024 to 2026). A category of psychiatric disorders which are characterized by anxious feelings or fear often accompanied by physical symptoms associated with anxiety. "This highlights the pivotal role of TLR4-mediated signaling in controlling neuroinflammation and its potential as a target for treating anxiety disorders." (PMID 39717701, 2024).
astrocytomas (3 papers, 2018 to 2023). "Here, we analyzed TLR4 expression in different grades of astrocytoma, and observed increased expression in tumors, mainly in GBM, compared to non-neoplastic brain tissue." (PMID 33446690, 2021). "First, we determined TLR4 expression in 140 human astrocytoma samples of different malignant grades." (PMID 33446690, 2021). "On the other hand, the median TLR4 expression in GBM cases was lower than in the other astrocytoma grades (AGII-AGIII)." (PMID 29912993, 2018). "This study aims to analyze the expression levels of plasmatic cell membrane TLRs (TLR1, TLR2, TLR4, TLR5, and TLR6) in human astrocytomas the most prevalent tumors of CNS different grades (II-IV)." (PMID 29912993, 2018). "We observed that TLR4 expression was higher in astrocytoma samples when compared to non-neoplastic samples." (PMID 33446690, 2021). "TLR1, TLR2, TLR4, TLR5, and TLR6 are involved in a diversity of cellular responses, ranging from cell proliferation to cell death, and as such they are the targets of the current study in astrocytomas." (PMID 29912993, 2018). "In this regard, experimental evidence on the increased cell surface expression of TLR1, TLR2, TLR4, TLR5, and TLR6 in astrocytoma samples compared to non-neoplastic brain tissues clearly revealed the involvement of these TLRs in the progression of astrocytoma." (PMID 37822929, 2023). "Here, we first recapitulated TLR4 expression in our cohort of 140 human astrocytoma of different grades of malignancy (26 AGII, 18 AGIII, and 96 GBM compared to 22 non-neoplastic [NN] brain tissue), and we next analyzed TLR4 signaling pathways." (PMID 33446690, 2021). "In the present study, higher expression levels of TLR1, TLR2, TLR4, TLR5, and TLR6 were demonstrated in human diffusely infiltrating astrocytomas (grades II to IV) in comparison to non-neoplastic brain tissue." (PMID 29912993, 2018). "In summary, increased cell membrane TLR1, TLR2, TLR4, TLR5, and TLR6 expressions were demonstrated in astrocytomas compared to non-neoplastic brain tissue, mostly in GBM group, and particularly in the mesenchymal subtype." (PMID 29912993, 2018).
atopic asthma (3 papers, 2012 to 2017). An asthma that is characterized by symptoms that are triggered by an allergic reaction caused by inhaled allergens such as dust mite allergen, pet dander, pollen and mold. "In contrast, TLR4 D299G has been linked to different levels of susceptibility to bacterial infections as well as a higher prevalence of atopic asthma in Swedish children." (PMID 28784091, 2017). "In fact, exposure to bacterial endotoxin—a ligand for TLR4—was shown to be inversely related to the incidence of atopic asthma, hay fever, and sensitization against aeroallergens in school-aged children." (PMID 22577387, 2012).